Y_RNA (Y RNA )
Gene: Miscellaneous RNA gene on chromosome 14 (20,679,411 to 20,679,512, forward strand). Ensembl gene ENSG00000199461.
Homologues: Orthologues: chimpanzee Y_RNA (100% identical), macaque Y_RNA (95% identical). Paralogues in human: RNY3 (93% identical), Y_RNA (93% identical), RNY3P1 (92% identical), Y_RNA (92% identical), Y_RNA (91% identical), Y_RNA (90% identical), Y_RNA (89% identical), RNY3P14 (88% identical), RNY3P16 (88% identical), Y_RNA (88% identical), RNY3P11 (87% identical), Y_RNA (87% identical), and 97 more.